REN (renin)
Diseases named in the same sentence as REN in open-access papers (continued):
Sharing a sentence is not in itself a finding about the gene and the disease.
diabetes (continued). "The most common medication classes involved in DRAs related to treatment effectiveness included Diuretics, Antithrombotic agents, Drugs used in diabetes, Agents acting on the renin-angiotensin system, and Lipid modifying agents." (PMID 35770091, 2022). "In our study, the most common medication classes were Diuretics, Antithrombotic agents, Drugs used in diabetes, and Agents acting on the renin-angiotensin system." (PMID 35770091, 2022). "Overall, 10.3% of all of the participants had diabetes and 23.4% had glomerulonephritis; 85.7% of all of the participants were prescribed renin–angiotensin–aldosterone system blocker at enrollment." (PMID 36151235, 2022). "Among the crude data, predictive factors including being female, DDD, aldosterone-renin ratio and diabetes mellitus showed publication bias." (PMID 36060937, 2022). "During the last 20 years, the outlook for diabetes patients with diabetic kidney disease has improved, probably because of the early aggressive lowering of blood pressure and blocking of the renin-angiotensin-aldosterone system." (PMID 36204481, 2022). "The implication of renin-angiotensin-aldosterone system (RAAS) components in the pathophysiology of diabetes-induced nephropathy have been well known for many years." (PMID 35176079, 2022). "The treatment options are also restricted to inhibitors of the renin-angiotensin system as well as maintaining the diabetes under control by managing hyperglycemia, blood pressure and dyslipidemia." (PMID 35712247, 2022). "In that study, the phosphate remained high after treatment and many patients with comorbidities found in CKD and HD patients (diabetes, coronary artery disease, smoking, and use of renin–angiotensin–aldosterone system inhibitors or statins) were excluded." (PMID 35999520, 2022). "The renin–angiotensin–aldosterone system‐blocker pathway prescribed ARBs/ACE inhibitors first for patients with diabetes, impaired renal function, and microalbuminuria; the standard pathway started patients on calcium channel blockers." (PMID 36153643, 2022). "The pooled prevalence of possible CKD was 10·0% (95% confidence interval 8.5‒11.4; mean pooled age 75, 53% women, 38% diabetes, 60% using renin-angiotensin-aldosterone system inhibitors)." (PMID 36090671, 2022). "Hyperglycemia is another important regulator of (pro)renin synthesis, and the CD has been suggested to be the origin of the elevated circulating prorenin levels in diabetes." (PMID 35710133, 2022). "More recent evidence has also shown that prorenin and renin levels are increased in the plasma and kidneys in diabetes." (PMID 34179130, 2021). "Drugs used to treat diabetes such as the renin-angiotensin system (RAS) inhibitors, including angiotensin-converting enzyme inhibitor (ACEI) and angiotensin receptor blocker (ARB)." (PMID 34957109, 2021). "Potential pathogenetic links between COVID-19 and diabetes include inflammation, effects on glucose homeostasis, haemoglobin deoxygenation, altered immune status and activation of the renin-angiotensin-aldosterone system (RAAS)." (PMID 34299225, 2021). "The control of blood glucose levels by various glucose-lowering drugs, the common use of inhibitors of the renin–angiotensin system, and the aging of patients with diabetes can alter the disease course of DKD." (PMID 34356375, 2021). "In the kidney, the renin-angiotensin system (RAS) is activated during diabetes mellitus and contributes to the development of renal tissue injury." (PMID 34226610, 2021). "Renin-angiotensin system blockers are recommended in patients with diabetes coexisting with HT, especially when proteinuria or microalbuminuria is present." (PMID 33953972, 2021). "Patients with PA were more often male, showed significantly higher BMI and blood pressure, higher prevalence of diabetes, lower potassium, higher aldosterone concentrations, and lower renin levels compared to EH." (PMID 33112272, 2021).
diabetes (continued). "The renin–angiotensin–aldosterone system (RAAS) plays an important role in the progression of diabetes to heart failure and DCM." (PMID 33682891, 2021). "Induction of diabetes in mice led to a significant increase in retinal expression and production of the renin-angiotensin system components, such as angiotensin II, AT1-R, and AT2-R." (PMID 34571920, 2021). "It is suggested that increased intrarenal renin is responsible for the development and progression of nephropathy in diabetes through increased intrarenal AT1 receptor signaling." (PMID 34830315, 2021). "In hypertensive people, the presence of obesity leads to overactivation of the sympathetic nervous and renin-angiotensin-aldosterone systems, as well as proinflammatory/pro-oxidative mechanisms, which are related to diabetes." (PMID 33926442, 2021). "The most common activities found were the dipeptidyl peptidase IV (DPP-IV) inhibitory activity related to diabetes, and the ACE and renin inhibitory activity and antithrombotic effects associated with cardiovascular diseases." (PMID 34681387, 2021). "DN is a frequent microvascular complication in diabetes but current treatments, such as blood glucose and blood pressure control and renin–angiotensin–aldosterone system inhibitors, remain suboptimal." (PMID 33044562, 2020). "As a result, macula densa cells trigger the reduction of renin release to suppress the renin-angiotensin-aldosterone system (RAAS) and vasoconstriction of the afferent arterioles to reduce hyperfiltration that is commonly associated with diabetes." (PMID 32767111, 2020). "It has been suggested that changes in urinary renin levels in patients with diabetes occur independently of changes in plasma renin, indicating involvement of the activated renal RAS." (PMID 33273645, 2020). "Renin-angiotensin-aldosterone system inhibitor (RAASi) therapy has been shown to improve outcomes among patients with congestive heart failure, diabetes, or renal dysfunction." (PMID 31910208, 2020). "The mouse studies indicated possible roles of renin-angiotensin and kallikrein-kinin systems and increased expression of TNF-α in the development of osteoporotic changes induced by diabetes and estrogen deficiency." (PMID 33204216, 2020). "Concerning comorbidities, 52.0% were hypertensive, 78.9% of them were treated with blockers of the renin-angiotensin system (RASBs); 28 % 28.8% had dyslipidaemia and 23.7% suffered diabetes." (PMID 32802142, 2020). "This is especially true given the comorbid conditions among patients with diabetes and with the frequent use of renin-angiotensin system blockers in this population, increasing the risk of renal dysfunction." (PMID 32382466, 2020). "Despite the aggressive blockade of the renin–angiotensin–aldosterone system, many patients with diabetes still progress to ESRD." (PMID 32992565, 2020). "Several clinical and experimental studies have suggested that the renin–angiotensin system (RAS) is activated during the development of cardiac dysfunction in diabetes." (PMID 32244448, 2020). "The special physiological/pathophysiological state of renin granulation in STZ-induced diabetes has turned attention towards estimating the number (pro)renin receptors in STZ-induced diabetic rats." (PMID 31049226, 2019). "Suggested factors include sympathetic nervous system overactivation (perhaps due to obesity, diabetes, metabolic syndrome), obstructive sleep apnea, dysfunction in activity of renin-angiotensin-aldosterone axis, sodium intake, and chronic kidney disease." (PMID 31057391, 2019). "In diabetes, (pro)renin expression is also elevated, treatment with a (pro)renin antagonist, such as handle reagent peptide (HRP), reversed the development of diabetic nephropathy." (PMID 31049226, 2019). "Diabetes has been documented to suppress the circulating RAS, causing a decrease in the blood levels of renin and angiotensin II." (PMID 31212580, 2019).
diabetes (continued). "Angiotensin II levels in the kidney are elevated in STZ-induced diabetes and renin granulation is also elevated in afferent arterioles." (PMID 31049226, 2019). "Hyperkalemia (HK) is the most common electrolyte disturbance observed in patients with kidney disease, particularly in those in whom diabetes and heart failure are present or are on treatment with renin–angiotensin–aldosterone system inhibitors (RAASIs)." (PMID 31119681, 2019). "Renin inhibitor can be a possible tool to prevent bone and tissue implication during the PD during the diabetes." (PMID 31333451, 2019). "Recognizing its importance as a pro-fibrotic stimulus, a number of groups have induced diabetes pharmacologically or genetically in rodent models that overexpress renin." (PMID 31467329, 2019). "Much research has shown that the renin-angiotensin-aldosterone system (RAAS) plays a critical role in diabetes." (PMID 30875840, 2019). "In STZ-induced diabetes, renin granulation in the afferent arteriole is higher than normal, while angiotensin II levels in the kidney are also elevated." (PMID 31049226, 2019). "Two other RCTs reported a significant suppression in plasma renin by vitamin D in patients with diabetes and coronary artery disease, respectively." (PMID 30057603, 2018). "In France, two studies showed that the prevention of diabetic nephropathy is not optimal in France, in particular the low detection rate of albuminuria and the insufficient use of inhibitors of the renin-angiotensin system in patients with diabetes." (PMID 29907091, 2018). "Evidence indicates that an over accumulation of uric acids can lead to endothelial dysfunction through nitric oxide degeneration or activation of the renin-angiotensin system, which results in insulin resistance and thus diabetes." (PMID 30693289, 2018). "The types of the most frequently stopped drugs in these groups were drugs for constipation, drugs used in diabetes, diuretics, agents acting on the renin-angiotensin system, lipid modifying agents, and analgesics." (PMID 29453677, 2018). "While renin-angiotensin system targeted therapies show promise in reducing incidence of cardiac arrhythmias and diabetes, additional research is necessary to further understand the mechanisms involved and confirm studies performed in small patient populations." (PMID 30534081, 2018). "The drugs which dose was most often modified were drugs used for diabetes (9% (n = 5)), minerals (9% (n = 5)), cardiac therapy (10% (n = 6)), and agents acting on the renin-angiotensin system (7% (n = 4))." (PMID 29453677, 2018). "Here, we have shown that iron accumulation during diabetes upregulates retinal renin expression in a GPR91-dependent manner." (PMID 29445185, 2018). "Inhibitors of the renin-angiotensin system have been shown to reduce cardiovascular events, decrease diabetic complications and can reduce incidence of new onset diabetes." (PMID 30534081, 2018). "In light of previous reports implicating retinal renin-angiotensin system in DR pathogenesis, our results reveal a novel relationship between diabetes, iron and renin-angiotensin system, thereby unraveling new therapeutic targets for the treatment of DR." (PMID 29445185, 2018). "Pericyte apoptosis and activation of the renin-angiotensin system are one of the leading early mechanisms of the impact of diabetes on retinal microvasculature, which probably explains decreased vascular density." (PMID 29614075, 2018). "The most common concomitant medications during the single- and double-blind periods were drugs used in diabetes, agents acting on the renin-angiotensin system, and lipid-modifying agents." (PMID 28383710, 2017). "NT-proBNP, age, male sex, renin, diabetes duration, Lp-PLA2 and 25-OH vitamin D3 were selected as significant mortality predictors for the final multivariate model." (PMID 28680124, 2017).
diabetes (continued). "The following seven variables were selected for the final multivariate model: NT-proBNP, age, male sex, renin, diabetes duration, Lp-PLA2 and 25-OH vitamin D3." (PMID 28680124, 2017). "Aliskiren was shown to increase adverse events in patients with diabetes and concomitant renin–angiotensin blockade." (PMID 28844155, 2017). "Miller and colleagues demonstrated that during the early stages of diabetes there was an increase in plasma renin activity, mean arterial pressure, and renal vascular resistance." (PMID 27652272, 2016). "Earlier studies observed that the level of inactive renin found in normal plasma was significantly higher in uncomplicated diabetes mellitus and greatly increased in diabetic nephropathy." (PMID 26753721, 2016). "Compared to those without CKD (N = 30), those with CKD (N = 36) were overall well matched with similar age, race, blood pressure, body mass index, use of renin-angiotensin antagonists, and smoking history, but were more likely to have diabetes (p < 0.01)." (PMID 27412615, 2016). "Subjects who experienced hypoglycemia tended to use combination therapy for diabetes management more frequently as well as an increased proportion of renin-angiotensin system (RAS) blockade (p <0.001)." (PMID 26890789, 2016). "Several of the drugs commonly prescribed to patients with diabetes target the renin–angiotensin system (RAS), a hormone system that regulates blood pressure and fluid balance." (PMID 26954482, 2016). "Apart from juxtaglomerular cells, the highest expression of renin (Prorenin) is observed in the connecting tubules and collecting ducts in diabetes patients." (PMID 26217336, 2015). "It has been reported that the tissue level of the renin angiotensin system behaves independently of PRA, especially in diabetes; the tissue renin-angiotensin system is activated even though PRA is low in diabetes." (PMID 25799069, 2015). "We defined T2D-ESKD candidate loci as genes which have been implicated in ESKD (diabetes associated or non-diabetes associated) either through direct (e.g. CNDP1, APOL1) genetic analysis or through compelling functional relationships (e.g. REN)." (PMID 24551085, 2014). "Renovascular hypertension superimposed on diabetes exacerbates development of chronic renal disease in db/db mice at least in part through interaction with the renin-angiotensin system." (PMID 24708836, 2014). "In hypertensive patients with diabetes, treatment with aliskiren, a direct renin inhibitor, reduced QT dispersion at 12 weeks after treatment." (PMID 25142437, 2014). "Our theory suggests that the number of AT1 receptors is downregulated not only in the SMC, but also to an extreme degree in the renin-granulated SMCs in diabetes." (PMID 24587998, 2014). "Insufficient vitamin D status and increased renin-angiotensin system (RAS) activity have been associated with renal-vascular disease and nephropathy in diabetes." (PMID 23971740, 2013). "We aimed to determine how single and combination antihypertensive therapy alters risk for diabetes mellitus (DM).Thiazide diuretics (TD), β blockers (BB), and renin–angiotensin system blockers (RASB) impact DM risk while calcium channel blockers (CCB) are neutral." (PMID 23752710, 2013). "We report that AT1a-KO mice develop diabetes-induced cardiac dysfunction, which is prevented by a renin inhibitor, as well as by an ACE inhibitor and ARB." (PMID 24215514, 2013). "Our study indicates that, in additon to diabetic nephropathy, direct renin inhibitor also has anti-proteinuric effect on non-diabetic glomerular disease." (PMID 23675422, 2013). "Surprisingly, the inactive precursor of renin, called prorenin, also circulates in blood, at concentrations that are ten times higher, and in diabetes and pregnancy even up to 100 times higher." (PMID 22543358, 2013).
diabetes (continued). "It has been reported that the level of local angiotensin II is increased in the kidneys of diabetes, although the circulating levels of renin are normal or even low in diabetic patients." (PMID 23957015, 2013). "We observed that the renin inhibitor aliskiren completely protected animals from developing cardiac dysfunction up to 10 wks of diabetes." (PMID 24215514, 2013). "Metabolic control of diabetes and control of hypertension with renin angiotensin blocker remain the most effective method to prevent the progression of glomerular problems of diabetes and to stop the progression of the early pathological features of DN." (PMID 25340129, 2013). "It has also been reported that diabetes is coupled with an activation of the renin-angiotensin system in the heart." (PMID 22347376, 2012). "Multiple lines of evidence suggest that increased activation of the renin-angiotensin system (RAS) is involved in the development of type 2 diabetes mellitus." (PMID 22768174, 2012). "Patients with diabetes were more likely to receive drugs acting on the renin-angiotensin system (RAS blockade), either an ACE-inhibitor or an angiotensin receptor blocker, either at baseline or at some time during the study." (PMID 21274458, 2011). "In diabetes, formation of prorenin, a precursor of renin, in the renal collecting tubule is increased." (PMID 21166600, 2011). "Experimental models of diabetes revealed that COX-2 expression is increased in the macula densa in this condition and is associated with enhanced production of vasodilatory PGs, renin-angiotensin system activation, and renal hyperfiltration." (PMID 27713354, 2010). "Blocking the renin-angiotensin system has been shown to prevent cardiovascular disease and delay the onset of diabetes." (PMID 17407587, 2007). "There is a growing body of evidence that the renin-angiotensin system (RAS) plays a pivotal role in the pathogenesis of diabetes and CVD in patients with hypertension." (PMID 23675001, 2006). "The renin-angiotensin system (RAS) plays a pivotal role in the pathogenesis of diabetes and cardiovascular disease (CVD) in hypertensive patients." (PMID 23675001, 2006). "However, some populations are at risk of hyperkalemia, including those living with kidney disease, diabetes mellitus, or heart disease, and those taking renin–angiotensin–aldosterone system inhibitors (RAASi)." (PMID 41010461, 2025). "Additionally, prolonged diabetes duration enhances renin–angiotensin–aldosterone system (RAAS) activity while reducing insulin-mediated vasodilation, further contributing to elevated blood pressure." (PMID 40822947, 2025). "A review of randomized studies suggests that mineralocorticoid receptor antagonists further reduce proteinuria in patients with diabetes mellitus or non-diabetes mellitus causes of CKD when combined with renin-angiotensin system blockers." (PMID 40678143, 2025). "In patients with diabetes, various medications used for diabetes or concomitant diseases may affect renin release, aldosterone production, or tubular potassium excretion capacity." (PMID 40717832, 2025). "In patients with diabetes, decreased plasma renin activity leads to hypoaldosteronism." (PMID 40498214, 2025). "ACE and Renin inhibitorAnti-hypertensionDPP IV inhibitorAnti-hyperglycemia(anti-diabetes)." (PMID 41585459, 2025). "Gastrointestinal (GI) complications are common in diabetes, but the role of the local renin-angiotensin-aldosterone system (RAAS) in gut remodeling remains unclear." (PMID 40650071, 2025). "The interplay between diabetes and chronic kidney disease involves complex mechanisms, including inflammation, oxidative stress, and alterations in the renin-angiotensin-aldosterone system, all of which can accelerate renal dysfunction in patients with diabetes." (PMID 38172731, 2024).